NOD1 (nucleotide binding oligomerization domain containing 1)
Diseases named in the same sentence as NOD1 in open-access papers (continued):
Sharing a sentence is not in itself a finding about the gene and the disease.
Chlamydia infection (4 papers, 2016 to 2025). "This in vitro data suggested that NOD1/NOD2/RIP2 signaling detects a host ER stress response to Chlamydia infection and induces inflammation." (PMID 32487756, 2020). "Overall, these data suggest that RIP2 and NOD1/NOD2 proteins serve to link ER stress induced by Chlamydia infection with the induction of inflammatory responses." (PMID 32487756, 2020). "Our in vivo infection data largely agree with these previous reports and demonstrate that NOD1/2- and RIP2-deficient mice have a significantly reduced ability to control Chlamydia infection." (PMID 32487756, 2020). "A previous study demonstrated that the endogenous IL-8 response to Chlamydia infections depends on NOD1 signaling via RIP2 as part of a signal system that requires multiple inputs for optimal IL-8 induction." (PMID 27557518, 2016). "Thus, NOD1/2 signaling contributes to optimal resolution of Chlamydia infection, but there are likely to be other innate sensors that compensate for the absence of this response to effect final clearance from the host." (PMID 32487756, 2020). "Thus, NOD1/2 might initiate ligand-independent induction of UPR-induced inflammation as a consequence of an ER stress response induced by Chlamydia infection." (PMID 32487756, 2020). "Together, these data suggest a redundant role for NOD1/2 and RIP2 signaling in the development of inflammatory responses to Chlamydia infection." (PMID 32487756, 2020). "In this study, we demonstrate that chlamydia infection can be detected by both NOD1 and NOD2 receptors in vitro, but that the kinetics of that signaling differs significantly with NOD2 signaling lagging behind that of NOD1." (PMID 40502116, 2025). "Furthermore in NOD1 knock-out mice, cytokine expression and pathology were the same after Chlamydia infection as wild-type mice demonstrating that NOD1 is not essential to elicit an innate immune response." (PMID 27002636, 2016).
Glucose intolerance (4 papers, 2017 to 2025). Glucose intolerance (GI) can be defined as dysglycemia that comprises both prediabetes and diabetes. "When probing the effects of Nod1-mediated dysglycemia, our model demonstrates that activation of Nod1 lowers fasting blood glucose coincident with significant glucose intolerance (i.e. increase in blood glucose levels in response to glucose challenge)." (PMID 28484277, 2017). "Correlation studies found an association between NOD1 and NOD2 expression and glucose intolerance." (PMID 37239938, 2023). "Furthermore, treatment of mice with gefitinib prevented Nod1-induced glucose intolerance in vivo." (PMID 28484277, 2017).
head and neck squamous cell carcinoma (4 papers, 2016 to 2025). A squamous cell carcinoma that arises from any of the following anatomic sites: lip and oral cavity, nasal cavity, paranasal sinuses, pharynx, larynx, and salivary glands. "NOD1 (nucleotide-binding oligomerization domain 1) is overexpressed in head and neck squamous cell carcinoma (HNSCC) cells, as is IL-8 in cancer cells." (PMID 27557518, 2016).
lung adenocarcinoma (4 papers, 2022). A carcinoma that arises from the lung and is characterized by the presence of malignant glandular epithelial cells. "Similarly, NOD1 and NLRP2 function as risk genes in pyroptosis-related prognostic gene signature related to pyroptosis of lung adenocarcinoma." (PMID 36457716, 2022). "Another comprehensive bioinformatics analysis also performed on lung adenocarcinoma identified a prognostic pyroptosis-related gene signature containing five genes (NLRP7, NLRP1, NLRP2, NOD1, and CASP6)." (PMID 36324154, 2022). "not only constructed a pyroptosis-related prognostic predication model involving 5 PRGs (CASP6, NLRP7, NOD1, NLRP1, and NLRP2) in lung adenocarcinoma, but also established a network of mRNA–miRNA–lncRNA closely relating to PRGs." (PMID 35912258, 2022).
pancreatic cancer (4 papers, 2015 to 2022). "Increased expression level of NOD1 in peripheral blood leukocytes of pancreatic cancer." (PMID 30548868, 2019). "For example, disorders of innate antibacterial response are of fundamental importance in the development of gastrointestinal cancers, including pancreatic cancer, and increased expression of TRAF6, TLR4, and NOD1 are detected in peripheral blood leukocytes of pancreatic cancer patients." (PMID 30294322, 2018).
pancreatitis (4 papers, 2020 to 2022). Inflammation of the pancreas. "Recognition of gut Gram-negative bacteria by toll-like receptor 4 (TLR4) and nucleotide-binding oligomerization domain 1 (NOD1) expressed by pancreatic acinar cells and immune cells causes pro-inflammatory cytokine responses in experimental pancreatitis." (PMID 35967861, 2022). "Previous work has demonstrated that NOD1 responses were the key factors in the development of pancreatitis, as reflected in the experimental pancreatitis caused by cholecystokinin hyperstimulation." (PMID 35811665, 2022). "In fact, mice deficient in TLR4 or NOD1 are highly resistant to induction of experimental pancreatitis." (PMID 35967861, 2022). "We clarified the molecular mechanism by which NOD1 activation caused CCKR-mediated pancreatitis." (PMID 34759844, 2021). "(2012), who found that the gut microbiota mediated cerulein-induced pancreatitis through activation of pancreatic acinar NOD1 to a much greater extent than TLR4." (PMID 35811665, 2022). "Activation of the NOD1 signaling pathway plays a crucial role in cerulein-induced mouse pancreatitis." (PMID 35811665, 2022).
parasitemia (4 papers, 2012 to 2024). "NOD1, a member of the cytosolic NOD-like receptor (NLR) family, also plays a role in controlling T. cruzi infection; Nod1−/− mice were shown to be very susceptible to T. cruzi, succumbing to the infection and displaying higher parasitemia and parasite loads in the spleen and heart tissues." (PMID 25197170, 2014). "Although the role of NOD1 in host cells infected with N. caninum remains unknown, NOD1 can mediate host defenses against bacterial, viral and other parasitic infections." (PMID 35999576, 2022). "In this work, Nod1−/− mice were shown to be very susceptible to T. cruzi, succumbing to the infection and displaying higher parasitemia and parasite loads in the spleen and heart tissues, although NOD1 deficiency does not impair the production of different cytokines as IL-12, TNF-α, IFN-γ, or IL-10." (PMID 22496959, 2012). "In mammals, NOD1/NOD2 interacts with RIPK2, leading to the production of proinflammatory cytokines, to play roles in autophagy and anti-bacterial, -viral and -parasitic infections." (PMID 38715616, 2024).
pneumonia (4 papers, 2014 to 2024). An acute, acute and chronic, or chronic inflammation focally or diffusely affecting the lung parenchyma, caused by an infection in one or both of the lungs (by bacteria, viruses, fungi, or mycoplasma.). "Human lung epithelial cells contribute to the clearance of attenuated K. pneumoniae by producing beta-defensins in a TLR2- and NOD1-dependent manner, which highlights the importance of NOD1 in respiratory pathogen elimination and in pathogen-evasion mechanisms in human pneumonia." (PMID 25253572, 2014).
abortion (3 papers, 2019 to 2024). the ending of pregnancy by removing a fetus or embryo before it can survive outside the uterus. "The NOD1 expression level in the placental villi from recurrent spontaneous abortion females is higher compared to normal pregnancy, and NOD1 inhibited the invasion of trophoblast cells during gestation." (PMID 36496806, 2022). "Lack of NOD1 and NOD2 expression in macrophages was sufficient to recapitulate the increase in pup viability that we previously showed for B. abortus-infected Nod1−/− Nod2−/− mice, suggesting a cell-type-specific role for NOD1 and NOD2 in placentitis and abortion." (PMID 31337727, 2019). "However, NOD1/NOD2 knockout mice were not completely resistant to B. abortus-induced abortion, which prompted us to identify additional cellular pathways involved in triggering placental and fetal pathology." (PMID 31337727, 2019).
Anxiety (3 papers, 2021 to 2025). Intense feelings of nervousness, tension, or panic often arise in response to interpersonal stresses. "NOD1 is important for maintaining physiological function of the gastrointestinal tract, regulating central and peripheral serotonergic biology, cognition, anxiety, and HPA axis activation." (PMID 40281288, 2025).
Autoimmunity (3 papers, 2014 to 2021). The occurrence of an immune reaction against the organism's own cells or tissues. "The microbiotic environment of the Nod1 mouse has now been shown to interact with the animal's hormonal milieu – with consequent impact on the expression of autoimmunity." (PMID 24711544, 2014).
Behcet disease (3 papers, 2016 to 2023). A chronic, relapsing, multisystemic vasculitis characterized by mucocutaneous lesions, as well as articular, vascular, ocular and central nervous system manifestations. "This study provides evidence that the CIITA and NOD1 gene are involved in the susceptibility to Behcet’s disease." (PMID 26833430, 2016).
C. perfringens infection (3 papers, 2017 to 2021). "Although both bacteria increased NOD1 gene expression (p < 0.001), preincubation with L. plantarum Lac16 significantly reduced the increased gene expression associated with C. perfringens infection (p < 0.01)." (PMID 34830269, 2021). "The C. perfringens infection significantly up-regulated the TLR2.2 mRNA expression (P < 0.05) and tended to increase the mRNA levels of NOD1 (P = 0.057) and NF-κB p65 (P = 0.073)." (PMID 29118744, 2017).
cardiac hypertrophy (3 papers, 2018 to 2025). "However, recent studies have revealed that MAVS acts nucleotide-binding oligomeric structural domain-containing protein 1/receptor-interacting protein 2 (NOD1/RIP2) downstream to promote cardiac hypertrophy in response to transecting pressure overload induced by aortic constriction (TAC)." (PMID 40040697, 2025). "Nod1-/- and RIP2-/- mice demonstrated better survival, enhanced cardiac function, and reduced cardiac hypertrophy during subjecting to TAC." (PMID 40040697, 2025).
depression (3 papers, 2021 to 2025). "Whereas NOD2 on our identified pleiotropic locus 16q12.1, as a recognition receptor in the NLR family, has been shown that mice deficient in NOD2 and NOD1 exert signs of stress anxiety and depression in the context of hypothalamic–pituitary–adrenal axis hyperactivity." (PMID 40226707, 2024). "The expression level of the 5-HT1A, DRD1, ADRA-2A, GABA-A α1, CNR1, NR3C2, NOD1, NLRP3 and MC4R; BDNF levels, glial activity and intestinal permeability were determined in chronic stress-induced depression in rats." (PMID 40281288, 2025).
endometrial cancer (3 papers, 2010 to 2025). Primary or metastatic malignant neoplasm involving the endometrium (mucous membrane that lines the endometrial cavity). "Ten polymorphisms were genotyped in 191 endometrial cancer cases and 291 controls using real-time PCR: NOD1 (rs2075822, rs2907749, rs2907748), NOD2 (rs5743260, rs2066844, rs2066845), TLR2 (rs5743708), TLR4 (rs4986790) and TLR9 (rs5743836, rs187084)." (PMID 20646321, 2010). "Kaplan-Meier survival analysis and T-tests were used to evaluate the influence of the NOD1, NOD2, TLR2, TLR4 and TLR9 polymorphisms on the age of diagnosis of endometrial cancer." (PMID 20646321, 2010). "For these reasons, we sought to determine if genetic variation in a number of TLRs and NOD genes (TLR2, TLR4, TLR9, NOD1 and NOD2) were associated with risk of developing endometrial cancer." (PMID 20646321, 2010).
endometriosis (3 papers, 2024 to 2025). The growth of functional endometrial tissue in anatomic sites outside the uterine body. "There is a significant upregulation of NOD1 and inflammatory cytokines in the ectopic endometrium, suggesting that NOD1 is associated with endometriosis." (PMID 38903689, 2024). "They found significantly higher levels of TLR-2 and -9, NOD-1 and -2, iNOS and eNOS mRNA, and CA 125 in the endometriosis group compared to the controls (p < 0.05)." (PMID 40227209, 2025). "Our study revealed that the NOD1 rs2075820 had lower (G>A) genotypes in endometriosis patients when compared with the control group." (PMID 40034240, 2024). "We also evaluated the association of three polymorphisms in the NOD1, NOD2, and PYDC2 genes with the clinical manifestations of endometriosis." (PMID 40034240, 2024). "A statistically significant difference in the distribution of the rs2075820 (NOD1 G/A) genotypes was observed between endometriosis patients and control subjects." (PMID 40034240, 2024). "However, the potential association between single nucleotide polymorphisms (SNPs) of the NOD1, NOD2, PYDC1, and PYDC2 genes and the predisposition to endometriosis risk remains unexplored." (PMID 40034240, 2024).
Hepatitis (3 papers, 2021 to 2023). Inflammation of the liver. "In conclusion, the elucidation of the association between NOD1/NOD2-mediated signaling pathways and liver diseases opens new avenues for the development of novel treatments for hepatitis, steatosis, and HCC." (PMID 36268029, 2022). "Our data show that NOD1 agonist treatment prevented LPS/D-GalN-induced fatal hepatitis through the upregulation of A20 expression in hepatocytes." (PMID 33746949, 2021). "Here, we provide evidences that NOD1 activation attenuated liver injury by demonstrating that pretreatment with C14-Tri-LAN-Gly protected against LPS/D-GalN-induced lethal hepatitis." (PMID 33746949, 2021). "Collectively, these results indicate that NOD1 agonist pretreatment protected mice from LPS/D-GalN-induced lethal hepatitis, probably by inhibiting hepatocyte apoptosis." (PMID 33746949, 2021). "Here, we identify a novel regulatory mechanism of macrophage RIPK3 on NOD1 function and the TRPM7-mediated cell death pathway in IR stress-induced liver inflammation." (PMID 37841640, 2023). "Our results highlight the importance of the macrophage RIPK3-mediated XBP1–Foxo1–Zc3h15 signalling as a critical regulator of the NOD1 and calcineurin/TRPM7 function in IR-triggered liver inflammation." (PMID 37841640, 2023). "In addition to C14-Tri-LAN-Gly, we have also studied the effect of another NOD1 agonist C12-iE-DAP, which is widely used, on LPS/D-GalN-induced hepatitis." (PMID 33746949, 2021).
Listeria infection (3 papers, 2009 to 2025). "E. coli has been shown to activate TLR4 and NOD1, whereas resistance to Listeria infection was related to the presence of functional NOD2, indicating that this receptor is engaged by HKLM." (PMID 19193240, 2009). "Furthermore, in murine BMDMs, Nod1 and Nod2 seem to have redundant functions with regards to Listeria infection." (PMID 28253332, 2017). "Nod1 or Nod2 deficiency alone does not result in a significant alteration in cytokine response to Listeria infection, while cytokine production is downregulated in Rip2KO and Nod1-Nod2DKO macrophages." (PMID 28253332, 2017).
liver diseases (3 papers, 2020 to 2022). "NOD1 is widely expressed in liver parenchymal and non-parenchymal cells and the liver is constantly exposed to gut-derived bacterial products, suggesting that NOD1 might be involved in liver diseases." (PMID 33746949, 2021). "The present study also suggests NOD1 as a therapeutic target for liver diseases." (PMID 33746949, 2021). "Taken together, our data strongly indicate that NOD1 is involved in the regulation of liver injury and could be a potential therapeutic target for liver diseases." (PMID 33746949, 2021). "Numerous studies have highlighted the crucial role of NOD1 in renal and liver diseases, in which NOD1 activation can evoke the immune response and amplify tissue damage, while blockade of NOD1 can act as a protective factor against such tissue injury by modulating PMNs." (PMID 33261639, 2020). "Therefore, it is likely that NOD1 participates in the progression of liver disease." (PMID 33746949, 2021). "Evidence has shown that NOD1 is partially responsible for the pathogenesis of polymorphonuclear leukocyte (PMN)-induced liver ischemia injury, and deletion of NOD1 has a neuroprotective effect on PMN-dependent liver disease." (PMID 33261639, 2020).
papillary thyroid cancer (3 papers, 2011 to 2024). "The upregulation of NOD1 expression is correlated with a favorable prognosis in patients with papillary thyroid cancer (PTC), as the activation of the NOD1 signaling pathway promotes PTC cell apoptosis." (PMID 39329913, 2024).
triple-negative breast carcinoma (3 papers, 2019 to 2023). An invasive breast carcinoma which is negative for expression of estrogen receptor (ER), progesterone receptor (PR), and human epidermal growth factor receptor 2 (HER2). "In the triple-negative breast cancer model, reducing the expression of NOD1 can significantly inhibit the proliferation of tumor cells." (PMID 36186792, 2022). "In this work, we applied high-throughput LC-MS/MS analyses to characterize the proteome of the Hs578T triple negative breast cancer-derived cell line, overexpressing either NOD1 or NOD2 receptors." (PMID 30791886, 2019). "In summary, we characterized eugenol administration significantly inhibiting the proliferation and metastasis of triple-negative breast cancer cells, mechanistically, our data highlighted eugenol could play an anti-tumor role by inhibiting NOD1-NF-κB signal pathway." (PMID 36923216, 2023).
type 1 diabetes (3 papers, 2016 to 2024). "To delve further into that finding, we used a cell-based reporter assay to assess NOD1 activation through circulating agonists in Akita mice—a mouse model of type 1 diabetes." (PMID 38336763, 2024). "Using the Akita mouse model, our investigation revealed a pivotal role for NOD1 in the progression of DR within the context of type 1 diabetes." (PMID 38336763, 2024). "However, the relevance of NOD1 to type 1 diabetes and diabetic vascular complications has remained relatively unexplored." (PMID 38336763, 2024).
ulcerative colitis (3 papers, 2009 to 2023). An inflammatory bowel disease involving the mucosal surface of the large intestine and rectum. "This is the first report on the prevalence of the NOD1 polymorphisms in patients with Ulcerative colitis from northern part of India." (PMID 19723304, 2009). "In the present study, we have attempted to study SNP in NOD1 gene in ulcerative colitis patients in order to determine if any significant mutation is associated with ulcerative colitis." (PMID 19723304, 2009). "The mutation E266K in the NOD1 gene observed in the Exon 6 region was not significant (P = 0.272) in ulcerative colitis patients of Indian origin when compared with the non IBD population." (PMID 19723304, 2009). "So far, association of NOD1 gene with ulcerative colitis patients has not been documented." (PMID 19723304, 2009). "However, a very similar gene encoding Nod1 protein still has not been well documented for its association with Ulcerative colitis patients." (PMID 19723304, 2009).
(HCMV) infection (2 papers, 2014 to 2021). "NOD1 induction of IFN-β depends on RIPK2, as RIPK2 knockdown does not confer the protective effects of Tri-DAP-induced IFN-β expression during HCMV infection." (PMID 33525590, 2021). "NOD1 and NOD2 transcripts were quantified starting from the time of HCMV infection and then at 2, 4, 6, 8, and 24 hpi." (PMID 24671169, 2014). "Consequently, the transcript level of NOD1 is induced upon HCV, norovirus, and human cytomegalovirus (HCMV) infection." (PMID 33525590, 2021).